STAT3 (signal transducer and activator of transcription 3)
Diseases named in the same sentence as STAT3 in open-access papers (continued):
Sharing a sentence is not in itself a finding about the gene and the disease.
papillary thyroid cancer (30 papers, 2008 to 2025). "Curcumin, for instance, enhances chemotherapy efficacy its combination with cisplatin in papillary thyroid cancer cells produced stronger STAT3 inhibition and apoptosis than either treatment alone." (PMID 41346617, 2025). "In this study, the relationship between STAT3 activation and the prognosis of papillary thyroid carcinoma (PTC) was retrospectively examined using immunohistochemical staining with an anti-STAT3 antibody." (PMID 41104968, 2025). "JAK2/STAT3 pathway also played a key role in driving angiogenesis and inflammatory crosstalk in papillary thyroid cancer cells, but there were no reports on this signaling pathway in the pathogenesis of thyroid nodules at present." (PMID 39494342, 2024). "In summary, this study shows that the elevated expression of PLD in papillary thyroid cancers plays a synergistic role in the transcriptional activation of STAT3 by interacting with RET/PTC." (PMID 18498667, 2008). "Another finding has highlighted that this combination could suppress JAK/STAT3 signaling pathways involved with papillary thyroid cancer cell growth and proliferation and may provide better therapeutic outcomes." (PMID 37367068, 2023). "Studies showed that miR-630 may inhibit metastasis and EMT of papillary thyroid cancer via the inactivation of JAK2/STAT3 signaling pathway." (PMID 35813296, 2022). "Indeed, the STAT-3 pathway is significantly upregulated in metastatic thyroid papillary cancers, suggesting a potential role for activated STAT-3 in lymphatic metastases." (PMID 22927847, 2012). "Consequent with this idea, we hypothesize that PLD synergistically functions to activate STAT3 signaling by directly interacting with thyroid oncogenic kinase RET/PTC in the papillary thyroid cancer cells." (PMID 18498667, 2008). "However, in papillary thyroid cancer, FTO acts as a tumor suppressor to inhibit APOE expression and hinder glycolysis via the IL-6/JAK2/STAT3 signaling pathway." (PMID 41184232, 2025). "Furthermore, TRIM14 promoted papillary thyroid carcinoma cell proliferation via the interaction with SOCS1, a negative regulator of the STAT3 activation." (PMID 33982666, 2021). "Based on the observation of high levels of PLD expression in human papillary thyroid cancer tissues, we investigated whether PLD plays a role in the regulating the RET/PTC-induced STAT3 activation." (PMID 18498667, 2008). "However, OB3 did not induce activation of ERK1/2, PI3K, or STAT3 in anaplastic thyroid cancer or papillary thyroid cancer cells." (PMID 28750624, 2017). "However OB3 did not induce activation of ERK1/2, PI3K and STAT3 in anaplastic thyroid cancer and papillary thyroid cancer cells (results not shown)." (PMID 27050378, 2016).
chronic kidney disease (29 papers, 2013 to 2025). Impairment of the renal function secondary to chronic kidney damage persisting for three or more months. "Previous studies, including our own, have shown that both NF-κB and STAT3 signal pathways are implicated in the pathogenesis of chronic kidney disease." (PMID 27732564, 2016). "We utilized pericyte-like cells 10T1/2, which we and others have used to study STAT3 and other pro-fibrotic pathways in chronic kidney disease." (PMID 39335615, 2024). "We aimed to observe not only the injury-ameliorating effects of STAT3 blockade in L-AKI but also to investigate the effects of STAT3 inhibition in chronic kidney disease conditions." (PMID 39367511, 2024). "We determined the inhibitory effect of autophagy in chronic kidney disease and confirmed that STAT3 decoy ODN effectively inhibited autophagy by inhibiting the expression of STAT3 transcription factors in the UUO group." (PMID 33806080, 2021). "The IL-6/JAK/STAT3 signaling is hyperactivated and therefore is a good target in several cancers, chronic kidney diseases, and cardiovascular diseases." (PMID 34067609, 2021). "STAT3, AKT and mitogen-activated protein (MAP) kinases, including ERK1/2, JNK, and p38, have been implicated in podocyte injury and the progression of chronic kidney diseases (CKD)." (PMID 23555556, 2013). "Notably, C188–9 significantly reduced phosphorylated STAT3 (pY705-STAT3) levels in skeletal muscle from both chronic kidney disease and C26 tumor-bearing mice, accompanied by preservation of muscle mass, grip strength, and myofiber size." (PMID 40704145, 2025). "Furthermore, research has shown that Chinese medicine can reduce proteinuria in mice with chronic renal failure by inhibiting the JAK2/STAT3 and PI3K/AKT signaling pathways." (PMID 40046619, 2024). "Furthermore, we found that STAT3 is activated in acute and chronic kidney diseases, and its deletion from pericytes protects mice from kidney fibrosis." (PMID 39335615, 2024). "TTI-101 is a Stat3 inhibitor that blocks muscle proteolysis in rat model of chronic kidney disease." (PMID 35812340, 2022). "In addition, activated STAT3 in tubular cells has been stated to be important in chronic kidney disease." (PMID 34233296, 2021). "Our findings indicate that HGF may have protective effects in AOPP-mediated damage in chronic renal failure by keeping the balance of AGE receptor through regulating the JAK2/STAT3 signaling pathway." (PMID 28465704, 2017). "Interestingly, STAT3 has been found activated also in wasting muscles from patients suffering from chronic kidney disease and very recently involved in the control of satellite cell expansion and muscle repair." (PMID 25460504, 2015). "Signal transducer and activator of transcription 3 (STAT3), downstream signaling of EGFR and HSP27, has been reported to be associated with AKI or chronic kidney disease (CKD)." (PMID 40230054, 2025). "We used data from a large genome-wide association study to examine whether common SNPs in any of the genes encoding the kidney aging transcription factors (STAT1, STAT3 and the canonical NFκB complex genes RELA and NFKB1) show an association with kidney function or chronic kidney disease." (PMID 26678048, 2015). "Various signaling pathways are involved in process of chronic kidney disease, such as Wnt/β-catenin, TGF-β/Smads, JNK/STAT3, and MAPKs." (PMID 28536642, 2017). "Furthermore, the knockdown or knockout of miR-204-5p results in substantial pathological changes in the kidneys as well as proteinuria, and the protective role of miR-204 in chronic kidney disease is related to SHP2 and STAT3." (PMID 39199205, 2024).
chronic kidney disease (continued). "Notably, IL-11 remains undetected in the serum of healthy individuals due to its predominant regulation of extracellular matrix (ECM) rather than immune responses, favoring alternative ERK activity over JAK/STAT3 activity in chronic kidney disease (CKD) settings." (PMID 38732588, 2024).
pancreatitis (29 papers, 2013 to 2026). Inflammation of the pancreas. "In pancreatic epithelial cells with a KrasG12D mutation, IL-17A can directly stimulate the pancreatitis mediator to regenerate islet-derived 3-β, leading to STAT3 activation, thereby promoting PDAC development." (PMID 39906741, 2024). "Exogenous recombinant IL22 protects mice against acute severe pancreatitis-associated lung injury by regulating the apoptotic balance to strengthen the pulmonary microvascular endothelial barrier via the STAT3 signaling pathway." (PMID 37189778, 2023). "In addition, genes targeting ADAM17 (Adam17ex/ex mice) and treatments (ADAM17 predomain inhibitors [A17pro]) improved experimental pancreatitis, which was associated with a reduction in the IL-6 transsignaling/STAT3 axis." (PMID 36969002, 2023). "IHC staining for CD45 or phosphorylated-STAT3 (p- STAT3) showed that rReg4 treatment halted the immune cell infiltration and inflammatory responses during caerulein-induced pancreatitis." (PMID 38769308, 2024). "The regulatory effects of S1P signaling on pancreatitis predominantly involve NF-κB, STAT3 phosphorylation, PERK/TXNIP/NLRP3, RhoA/ROCK, and AMPK/mTOR pathways as well as IFN-γ and TGF-β1." (PMID 39519028, 2024). "Stimulate the pancreatitis mediator to regenerate islet-derived 3-β, leading to STAT3 activation, thereby promoting PDAC development." (PMID 39906741, 2024). "The results showed that phosphorylated STAT3 increased in the pancreatitis condition and that this increase was rectified by IL-37." (PMID 36166295, 2022). "Notwithstanding, we are still in the dark about the mechanism of the SOCS5/JAK2/STAT3 pathway in lung damage elicited by pancreatitis." (PMID 36333771, 2022). "In accordance with these findings, here we found higher levels for both NF-κB and STAT3 activation in the livers of the PGC-1α KO mice with pancreatitis." (PMID 32961723, 2020). "It is noteworthy that ablation of pancreatic STAT3 exacerbates cerulein-induced pancreatitis and demonstrates a protective effect of STAT3 against pancreatitis." (PMID 24606867, 2014). "STAT3 is a critical component of pancreatitis as its deletion protects against pancreatitis." (PMID 37373094, 2023). "In addition, upregulation of the ADAM17/IL-6 transsignal/STAT3 axis is a feature in patients with pancreatitis." (PMID 36969002, 2023). "However, loss of Tbx3 leads to overshoot proliferation of acinar cells, accumulation of fibrosis, and enhanced inflammatory stimuli, Il6-Jak-Stat3, and acinar cell-specific NF-κB signaling during pancreatitis." (PMID 36941669, 2023). "Therefore, a probe into the JAK2/STAT3 pathway mediated by SOCS5 helps us better understand the exact mechanism of lung damage elicited by pancreatitis." (PMID 36333771, 2022). "Interestingly, hydrostatin-SN10 cramps the IL-6-triggered activation of the JAK2/STAT3 pathway, lessens cell apoptosis, inflammation, and oxidative stress and mitigates lung damage induced by pancreatitis." (PMID 36333771, 2022). "In addition, studies have shown that activation of STAT3 aggravates AP-related liver damage in cerulein-induced AP in mice, which is consistent with our study result that STAT3 activation in pancreatitis leads to damage to tight junctions." (PMID 35096833, 2021). "In addition, pancreatic signal transducer and activator of transcription 3 (STAT3) has been found to protect mice against cerulein-induced pancreatitis." (PMID 33806041, 2021). "By taking into account our previous studies, in which the plasma levels of IL-6 increased in the PGC-1α KO mice with pancreatitis, we considered studying whether NF-κB and STAT3 activation are involved in inducing Nos2 in the liver upon PGC-1α deficiency." (PMID 32961723, 2020). "We therefore also analyzed the activation status of STAT3 and MAPKs in NEMOWT and NEMOΔCol1a2 mice after experimental pancreatitis." (PMID 35624133, 2022).
pancreatitis (continued). "It is also accompanied by STAT3 hyperactivation, probably due to the high IL-6 plasma levels achieved in PGC-1α KO mice during pancreatitis." (PMID 32961723, 2020). "Although we did not investigate the specific role of IL11 in the immune response in pancreatitis, we found that blocking IL11 signalling had anti-inflammatory effects and reduced IL6, IL1β and TNFα protein levels as well as diminishing NF-κB and STAT3 activation." (PMID 35408908, 2022). "We also observed a marked increase in the binding of p65 to p-STAT3 in the obese mice with pancreatitis, which supports the notion that lack of PGC-1α in obese mice livers may be associated with inducing Nos2 during AP." (PMID 32961723, 2020). "However, the lack of PGC-1α markedly increased the binding of p65 to p-STAT3 in KO mice with pancreatitis, suggesting that the induction of PGC-1α in the liver during AP may inhibit the formation of the p65/p-STAT3 complex." (PMID 32961723, 2020).
Myocardial fibrosis (28 papers, 2012 to 2025). "Aberrant JAK2/STAT3 signaling has been linked to enhanced fibroblast transformation, potentially leading to myocardial fibrosis and exacerbating cardiac dilatation and dysfunction." (PMID 40290189, 2025). "In summary, QSYQ inhibits NLRP3 inflammatory vesicles and inflammatory signaling pathways such as TGFβ1/Smads, STAT3, and NF-κB, and has multi-target anti-myocardial fibrosis properties." (PMID 40881586, 2025). "IL-10 is generally believed to inhibit myocardial fibrosis through activation of the STAT3 signaling pathway." (PMID 40881586, 2025). "Taken together, the JAK2/STAT3 pathway promotes myocardial fibrosis by promoting inflammatory responses, inducing differentiation of myofibroblasts, and transmitting the apoptotic effects of TGF-β." (PMID 40881586, 2025). "IL-6 and heat shock protein 90 (Hsp90) synergistically activate the signal transduction and transcriptional activator 3 (STAT-3) signaling pathway, leading to excessive collagen synthesis and contributing to the development of myocardial fibrosis." (PMID 40881586, 2025). "One study reported that exercise promoted the expression of CCDC80tide, inhibited Janus kinase 2 (JAK) activity, and activated signal transducer and activator of transcription 3 (STAT3), ultimately leading to an improvement in myocardial fibrosis." (PMID 39796197, 2025). "Regarding fibrosis, the antifibrotic effect of STAT3 inhibitors is receiving attention, but there has been little research on their ability to inhibit myocardial fibrosis." (PMID 38495094, 2024). "In stress overload-induced myocardial fibrosis, elabela and Fer-1 alleviate late concomitant myocardial fibrosis via the IL-6/STAT3/GPX4 signaling pathway." (PMID 39358326, 2024). "STAT3 has also been demonstrated to be directly involved in regulating myocardial fibrosis, which is characterized by myofibroblast activation and accumulation of extracellular matrix (ECM)." (PMID 36743695, 2023). "Some studies on the mechanism by which Stat3 exacerbates myocardial fibrosis showed that Stat3 is bound with COL1A1 and COL3A1 promoter and activates their transcription." (PMID 37891701, 2023). "First, we only investigated the role of CaMKII/Stat3 in regulating myocardial fibrosis with the inhibitors at the cellular level instead of the animal level." (PMID 37891701, 2023). "Pretreatment with KN-93 (a CaMKII inhibitor) blocked GF-induced Stat3 activation and significantly suppressed myocardial fibrosis." (PMID 37891701, 2023). "We also verified that muscone reduces myocardial fibrosis, decreases proinflammatory cytokine secretion, and inhibits, thus exerting cardioprotective effects through the activation of the STAT3, TGF-β/SMAD, and MAPK signaling pathways." (PMID 38158445, 2023). "CaMKII activation played an essential role in this process by activating Stat3, which led to increased myocardial fibrosis." (PMID 37891701, 2023). "Results showed that the mortality of STAT3 iCKO mice was increased, myocardial fibrosis was significantly worsened, and heart function deteriorated." (PMID 36225565, 2022). "Our study demonstrates that n‐butylidenephthalide protects against myocardial fibrosis in infarcted rats for targeting the PI3K/STAT3 signalling pathway." (PMID 31313516, 2019). "The JAK2/STAT3 pathway is activated by the binding of inflammatory cytokines, such as IL-6, to its specific receptor and stimulates the expression of cytokines, such as IL-6, thereby increasing the inflammatory response and promoting myocardial fibrosis." (PMID 40881586, 2025). "Recent research has demonstrated that ILs contribute to myocardial fibrosis via the STAT3 pathway." (PMID 38495094, 2024). "However, the role of Stat3 activation in myocardial fibrosis induced by GF and upstream events leading to Stat3 activation still needs to be elucidated." (PMID 37891701, 2023).
Myocardial fibrosis (continued). "PTX3 can counteract the myocardial fibrosis by inhibiting the IL-6/STAT3 pathway, implicating that PTX3 KD may acts as a therapeutic target for HF after MI." (PMID 35522573, 2022). "For example, THBS1 promotes myocardial fibrosis by activating the TGF-β signalling pathway, whereas STAT3 affects cardiomyocyte proliferation and apoptosis by regulating cytokine signalling." (PMID 40427439, 2025). "In summary, the inflammatory factor IL-6 promotes the development of myocardial fibrosis by activating inflammatory signaling pathways such as MAPK and STAT3 and activating TGFβ-1 growth factor." (PMID 40881586, 2025). "While further research is required to elucidate its role in various types of myocardial fibrosis, the JAK/STAT3 signaling holds promise as a therapeutic target for cardiac fibrosis due to its connection between cardiac inflammation and fibrosis." (PMID 38495094, 2024). "Signal transducer and activator of transcription 3 (STAT3), a member of STAT family, is a transcription factor, which can inhibit the degradation of ECM and regulate myocardial fibrosis." (PMID 35264961, 2022). "Additionally, myocardial fibrosis is one of the typical pathological alterations of HCM, and PKM2 can also be involved in promoting cardiac fibrosis via mechanisms such as JAK2/STAT3 signal activation." (PMID 40271123, 2025). "In addition, TGF-β/Smad signaling pathway, JAK2/STAT3 signaling pathway, and P38 MAPK signaling pathway also play important roles in myocardial fibrosis." (PMID 40881586, 2025). "Moreover, Ephrinb2-mediated myocardial fibrosis involves the activation of the TGF-β/Smad3 and STAT3 pathways." (PMID 38495094, 2024). "Phosphorylated STAT3 into the nucleus can accelerate the transcription and expression of the CCND1 gene, which drives the cell cycle of cardiac fibroblasts from the G1 phase to the S phase and accelerates myocardial fibrosis." (PMID 38402401, 2024). "Thus, m6A modification may represent a potential therapeutic target for controlling myocardial fibrosis and improving outcomes in DCM, given its impact on the JAK2/STAT3 pathway." (PMID 40290189, 2025).